CD4 (CD4 molecule)
Diseases named in the same sentence as CD4 in open-access papers (continued):
Sharing a sentence is not in itself a finding about the gene and the disease.
infection (continued). "Nevertheless, CD4 CTL appear to be prominent in infections that typically target APC or B cells, particularly those mediated by CMV, EBV, and dengue virus (DENV), and also HIV-1 that targets HLA class II+ activated CD4 T cells themselves." (PMID 28167943, 2017). "Downstream analysis revealed that the gene expression profile of HIV-1-infected, microbe-exposed LP CD4+ T cells predicted a strong infection, cell cycle perturbation and cell death outcome." (PMID 28241075, 2017). "We demonstrated that anti-infection activity with the bivalent flagellin immunization relatively abrogate in in vivo depletion of CD4+ T lymphocytes." (PMID 29201922, 2017). "Such MAP specific CD4+ T cells home to the site of infection and are thought to restrict bacterial growth." (PMID 28361039, 2017). "Trans-infection of CD4+ T cells is significantly more efficient than cell-free HIV infection, prompting the notion that DCs promote transmission by increasing the efficiency of T cell infection." (PMID 28207890, 2017). "The importance of CD4+ T cell recognition for AM infection control implied poor CD8+ T cell recognition." (PMID 28394921, 2017). "This suggests that macrophages are not an important source of viral replication in the initial stages of infection, emerging only later, as the virus adapts to infect cells with a lower CD4 density at the surface." (PMID 29250073, 2017). "Several studies have shown that during AHI up to 80% of CD4 memory T-cells in GALT is destroyed within the first 3 weeks of infection." (PMID 29354131, 2017). "Here, we show that Y. pseudotuberculosis directly interacts with CD4+ T cells during the acute phase of infection and exemplify an involvement of Th17 cells and Tregs in the pathomechanism of disease." (PMID 28378044, 2017). "This is in consonance with the recommendation by the Panel on Antiretroviral Guidelines for Adults and Adolescents that diagnosis of HIV be made early in the course of infection so as to initiate therapy early and at any CD4 count." (PMID 28119277, 2017). "Following brain TMEV infection, CD4+ and CD8+ T cells can be primed in the periphery and they subsequently infiltrate into the CNS53." (PMID 28290524, 2017). "The bacteria spread intracellularly, and CD4 and CD 8 T cells are essential for controlling the infection." (PMID 28376817, 2017). "At 6 days post infection (dpi), absolute CD4+ T cell counts were calculated by flow cytometry and automated cell counting relative to mock controls." (PMID 28241075, 2017). "In this study we have shown that IL-17-secreting cells were not only produced early in infection (day 18), but also late during the recovery process (day 168) and that both CD4+ and CD8+ T cells are sources of IL-17." (PMID 28904342, 2017). "Before infection, old ChRM had a significantly lower number of naïve CD4+ T cells (213.8 cells/μl) than did young macaques (503.4 cells/μl, P = 0.008)." (PMID 28232735, 2017). "Adaptive immunity critically contributes to control acute infection with enteropathogenic Yersinia pseudotuberculosis; however, the role of CD4+ T cell subsets in establishing infection and allowing pathogen persistence remains elusive." (PMID 28378044, 2017). "Our data showed increased numbers of naïve CD4+ T cells in the lungs of Nlrp3−/−, Casp1/11−/−, and Asc−/− compared with WT mice at weeks 2, 4, and 10 of infection." (PMID 28740491, 2017). "Another important feature of experimental infection with T. cruzi is the massive increase in apoptotic, activation-induced cell death in CD4+ T lymphocytes." (PMID 29163503, 2017). "In fact, the expansion of CD4+CD28- T cells in GPA is suggested to be driven by CMV infections, and is associated with increased risk of infection and mortality." (PMID 28615072, 2017). "The EC and TX patient groups were comparable with respect to age, gender, CD4 counts, and length of infection." (PMID 29196729, 2017).
infection (continued). "Future studies should examine differences in the memory CD4 T cell and B cell responses following infection in outbred mice as well as differences in the responses of innate immune cells." (PMID 29213267, 2017). "The infection of monocytes by HIV is thought to arise from virus released from re-activated infected CD4+ T cells in the blood or infection at the bone marrow level." (PMID 29088095, 2017). "Neutrophil count, B cells, CD4, CD8, NK cells, DC cells, and monocytes were evaluated and no immune cell parameter was associated with increased risk for infection." (PMID 29051761, 2017). "This allowed Lgals1−/− CD4+ T cell activity to be measured in a predominantly WT immunological background and compared with appropriate WT control CD4+ T cells following infection." (PMID 29075269, 2017). "CD4+ T cells were isolated from spleens 7 days after infection and enriched for PmpG-Tet+ CD4+ T cells using magnetic columns." (PMID 28106821, 2017). "This appears to be the case, as IL-2+MC, more than IL-2+CD90.2 or IL-2+CD4+ T cells, were expanded in vivo, early in infection, particularly in Cftr−/−mice." (PMID 28090087, 2017). "Mice lacking the mannose receptor died significantly faster than wild type mice, with higher lung fungal burdens at 4 weeks after infection, and they displayed impaired CD4+ T cell responses to mannoprotein." (PMID 29371564, 2017). "While it is well-understood that T cells, particularly CD4+ T cells, are required to control M. tuberculosis infection, the particular T cell effector functions that lead to control of infection continue to be debated." (PMID 29066547, 2017). "One month after infection, 38% of CD4+ and 23% of CD8+ IL-7neg T cells expressed PD-1, a marker of T-cell activation/exhaustion." (PMID 29112951, 2017). "Individuals infected with HIV-1 strains with TDR have a rapid depletion of CD4 cell count during the first year of infection." (PMID 28178281, 2017). "From a set of manually curated genes known to be involved in CD4+ T cell activation or effector function we also found evidence of significant T cell activation at 28 days of infection." (PMID 28103263, 2017). "This notion was supported by improved parasite clearance early during infection in the liver in Lgals1−/− animals, at a time when effector CD4+ T cell responses were being initiated." (PMID 29075269, 2017). "In another study, self-healing of the infection in mice correlated with the expansion of IFNγ and IL-17-producing CD4 cells, suggesting the existence of other active mechanisms to regulate local inflammation." (PMID 29163510, 2017). "It was described that T. cruzi infection triggers activation-induced cell death (AICD) of CD4+ T lymphocytes during the acute phase of infection." (PMID 28536576, 2017). "In persistent-infection granuloma-like structures from groups A, B, and C, the dynamics of CD4+ T cells was essentially unchanged during the course of infection, while CD8+ T cells significantly decreased." (PMID 27799331, 2017). "Here, an elevated CD4 surface density promotes high HIV-1 envelope-CD4 avidity and ensuing infection." (PMID 28122636, 2017). "Comparison of genes differentially expressed in the four cell types before infection revealed high expression of CD4 in THP-1-derived macrophages and low expression of CHMP4C (charged multivesicular body protein 4C)." (PMID 28442752, 2017). "En effet, ces stades correspondent à la survenue d'infections opportunistes graves qui apparaissent quand le taux de CD4 est inférieur à 200/mm3." (PMID 28748017, 2017). "It is widely known that the progression of HIV disease is directly related with the time of infection, with late HIV infections associated with CD4+ cell depletion and increased HIV replication." (PMID 28910347, 2017). "Adoptive transfer of immune CD4+ T cells, however, protects C3H/HeN mice against lethal infection with R. conorii." (PMID 28770333, 2017).
infection (continued). "In controlled-infection granuloma-like structures, the CD4+ T cell proportions fluctuated between 45% and 53%." (PMID 27799331, 2017). "For this purpose, we isolated CD4+ T cells from either naïve or R. typhi-infected BALB/c wild-type mice on day 7 post infection and incubated the cells with R. typhi-infected macrophages." (PMID 28222146, 2017). "We here assessed IL-7 expression and comprehensively studied chemokine networks and immune cell subsets in the gastrointestinal tract of Chinese rhesus macaques during acute SIVmac251 infection, with a particular focus on CD4+ macrophages and T-cells." (PMID 28579989, 2017). "Whereas, following natural infection, the majority of effector/memory CD4+ and CD8+ T cells recognized either gB or IE-1, respectively, and pp65." (PMID 29112951, 2017). "This particular phase follows 2–4 weeks post-infection (pi) and is evident by high viral RNA loads in the plasma, and a reduction in peripheral CD4+ T cells." (PMID 29259605, 2017). "CD4 T cells with cytotoxic functions have been reported during a wide range of infections, including HIV, CMV, EBV, mouse CMV, acute lymphocytic choriomeningitis virus, influenza virus, and ectromelia virus infections." (PMID 29133794, 2017). "This suggests a transient regulatory CD4+ T cell response early in infection before Th1 CD4+ T cells significantly increase." (PMID 28103263, 2017). "We chose this time point because infection had largely resolved in the liver and effective CD4+ T cell-mediated, concomitant immunity was established." (PMID 29075269, 2017). "HIV-1 pathogenesis is characterized by the progressive infection and depletion of CD4+ T lymphocytes that normally coordinate the adaptive T and B cell response to defend the host from intracellular pathogens." (PMID 28289418, 2017). "In a chronic infection, IL-21 production by Tfh cells has been shown to be the primary mechanism by which CD4 T cells help maintain CD8 T cell effector functions at late stages of infection." (PMID 28715493, 2017). "We recently identified two microRNAs, miR-221 and miR-222, which limit HIV-1 entry during infection of monocyte-derived macrophages (MDMs) by down-regulating CD4 expression." (PMID 29301198, 2017). "There is an infiltration of CD4+ T cells in the gastric mucosa; therefore, several studies have tried to address the inefficiency of the host response in clearing the infection." (PMID 28512631, 2017). "Incidence was estimated using a biomarker for recency of infection (stratified extrapolation approach) and 2 back-calculation models (CD4 and Bayesian hierarchical models)." (PMID 28159730, 2017). "Our results indicate that expression of the MHC H-2bxd haplotype on the C57BL background results in the induction of a larger frequency of CD4 T cells following Cl-13 infection than is elicited in mice expressing the H-2bxd haplotype on the BALB background." (PMID 28715493, 2017). "Neutrophils start accumulating in the colon at the early stage infection, followed by B cells at a later stage; CD4+ T cells are detected from day 14 postinfection." (PMID 27821583, 2017). "Increase in frequency of α4β7+ CD4 T cells in the FGT is shown to enhance infection in vaginal explants, and blocking α4β7 protects macaques from vaginal SHIV acquisition." (PMID 28570576, 2017). "This is a list of cell cycle-associated genes that showed more than 2-fold modulation in primary CD4+ T cells with HIV-1 NL4–3 infection." (PMID 28184007, 2017). "After 2 and 10 weeks of infection, CD4+ IL-17+ cells appeared in higher numbers in the lungs of IDO1−/− mice when compared with their WT controls." (PMID 28791025, 2017). "Total CD4+ T cells were purified from animals pre-infection and cultured for 24 h at 37 °C in CO2 incubator with or without IL-2 treatment, and the exosomes were isolated, quantified and kept in −70 °C for use." (PMID 29142313, 2017).
infection (continued). "At 8 days post infection, CD4 T cell responses were also directly compared between secondary and primary x139 infections using an IL-2 Elispot assay and HA-specific antibody levels were assessed using an HA protein ELISA." (PMID 28493882, 2017). "It is known that memory CD4 T cells are able to rapidly recruit innate immune effectors to the lung following infection, leading to enhanced viral clearance and decreasing the abundance of antigen." (PMID 28493882, 2017). "Infection similarly increased the percentage of IFN-ɣ expression in cultured CD4+ and CD8+ splenocytes from PBS-inoculated and TSf-ISPA immunized mice as compared to splenocytes from non-infected mice." (PMID 28938533, 2017). "In contrast to TGF-beta+ Treg cells, the levels of CD4+CD25+ T cells remained unchanged during the infection and transformation phase of the disease." (PMID 29267390, 2017). "Although the estimated CD4 distribution suggests that approximately half of them are in an early stage of infection, a significant proportion are estimated to have late-stage infection, suggesting that more efforts are needed to test and diagnose these people." (PMID 28953320, 2017). "Work in renal transplantation has demonstrated that the emergence and expansion of CD4+CD28− T cells in CMV-seronegative (CMV−) graft recipients directly results from infection by a CMV-seropositive (CMV+) graft." (PMID 28303136, 2017). "PbNK65 hrfΔ infections correlated with a reduction of CD4+PD-1+CD62L− and CD8+PD-1+CD62L- cells, which are memory effector T cells." (PMID 28831137, 2017). "When CD8+ T cells were eliminated, CD4+ T cell depletion increased virus titers and AM infection significantly more than did IFNγ neutralization." (PMID 28394921, 2017). "While anti-HIV CD4 T cells are instrumental to the immune response, they are also the primary targets of infection." (PMID 28893280, 2017). "We examine the effector mechanisms used by cytotoxic CD4 cells, the phenotypes that describe this population, and the transcription factors and pathways that lead to their induction following infection." (PMID 28167943, 2017). "Among six CD4 mutants, T81A and S125A abolished one hydrogen bond between the two molecules and reduced the efficiency of infection." (PMID 28429756, 2017). "FoxP3+ and IL‐10+ frequency within CD4+ T cells was significantly higher in peritoneal exudate cell PECs and spleen cells of E. multilocularis infected (AE‐WT) mice at 4 months post‐infection (p.i.)when compared to non‐infected WT‐controls." (PMID 28621034, 2017). "Upon antigenic stimulation, CD4+ T cells adopt one of two opposing fates: a helper T (Th) cell specialized in supporting the clearance of infections, or a regulatory T (Treg) cell that functions to attenuate immune responses." (PMID 28824171, 2017). "The high CD4+/CD8+ T lymphocyte ratio contributed to controlling infection within granuloma-like structures." (PMID 27799331, 2017). "Since DTH responses can be elicited at sites distal to the initial site of infection, these results confirm that CD4+ TRM are distributed and can function throughout the skin." (PMID 28419151, 2017). "To avoid any possible detection of parasite DNA carried with the CD4+ T cells isolated from infected hamsters, we used a luciferase-transfected L. donovani strain for the in vitro macrophage infections and measured parasite burden by luciferase activity." (PMID 28103263, 2017). "We compared the serologic and cellular immune profiles of treated HIV-infected individuals with similar durations of infection and preserved CD4 counts (> 350 cells/microliter) by hepatitis B vaccine (HBV) response before and after vaccination." (PMID 28580437, 2017). "Transmission studies of SIVmac in rhesus monkeys have suggested that inflammatory responses lead to T-cell influx and early infection of activated CD4+ T cells [reviewed in Ref." (PMID 29056936, 2017).
infection (continued). "Induction of long lasting CD4+ central memory T cells in the immunized animals post infection, affirms the superior immunogenicity of in-house fabricated fibril based vaccine." (PMID 29230211, 2017). "Affinofile cells can be induced to express varying levels of surface CD4 in a controllable fashion, allowing for standardized and reproducible infection of cells across a wide, physiologically-relevant range of CD4 surface densities." (PMID 28122636, 2017). "ART was first recommended by the World Health Organisation (WHO) for HIV-infected patients with moderate and advanced stages of infection, at a CD4 count ≤200 cells/μL in 2002 and a CD4 count ≤350 cells/μL in 2010." (PMID 29155832, 2017). "Reflecting the inclusion criteria, the population had advanced infection; median CD4+ cell count was 86 cells/μl, and 23% had previously been diagnosed with a WHO stage 4 illness." (PMID 28328795, 2017). "Penetration of mucosal barriers has been shown in both cases to be a rapid but inefficient process resulting in focal infection of few mucosal CD4+ cells, with productive host infection frequently ensuing from a single transmitted-founder virus." (PMID 28472201, 2017). "We demonstrate that this interaction involves their CRD domains, which is relevant in inhibiting DC-SIGN-mediated HIV-1 trans-infection of CD4+ T cells." (PMID 28824609, 2017). "At day 14 post-infection, numbers of CD4+ and CD8+ T cells in perigonadal fat remained unaltered in contrast to lung tissue where higher numbers of both populations were identified." (PMID 29040326, 2017). "Cellular immunity, including CD4 and CD8 T-cells specific to membrane antigens, also rapidly declined from 1 year after infection, as measured by enzyme-linked immunospot (ELISPOT) assays and flow cytometry." (PMID 29259327, 2017). "In order to validate this panel in vivo, we measured the frequency of CD4 T cells responding to each peptide during PbA pRBC infection." (PMID 28935714, 2017). "Using a peptide-based priming strategy, we found that selective expansion of the anti-HA CD4 T cell memory repertoire enhanced HA-specific antibody production upon heterosubtypic infection." (PMID 28493882, 2017). "Consistent with the results obtained in Jurkat T cells, knockdown of ABIN1 increases HIV-1 replication in CD4+ T lymphocytes to twofold to threefold at day 1, sixfold to eightfold at day 3, and about threefold at day 5 post infection." (PMID 28193275, 2017). "HIV infection can induce thymic damage through direct infection and killing of thymocytes, apoptosis, or disruption of the thymic stromal architecture, resulting in defective thymopoiesis and apoptosis of CD4+ T-cells." (PMID 29209103, 2017). "More detailed analysis clarified that while Vpr was important for virus replication in primary monocytes and differentiated macrophages, it was superfluous for the infection of resting or stimulated peripheral blood mononuclear cells or CD4+ cell lines." (PMID 28075409, 2017). "We first noticed that the amplitude of the total parasite‐specific CD4 response (as indicated by the pRBC‐loaded DC condition) was ~fourfold lower than at day 6 post‐infection with pRBC." (PMID 28935714, 2017). "Due to the non-competing nature of the 2W and LLO peptides for their cognate T cell receptor, activated LLO+ CD4+ T cells would only result from LdWT infection whereas activated 2W+ CD4+ T cells would only result from LdCen−/− infection." (PMID 29312315, 2017). "In fact, the acute phase of infection in the adult model occurs approximately 2 to 4 weeks p.i. and is characterized by infiltrating CD4+, CD8+, and plasma cells." (PMID 28446679, 2017). "Given the fact that HIV infection accelerates both the production and the destruction of CD4+ T-cells, in the early stages of the infection, there is constant replacement of dying CD4+ T-cells with native CD4+ T-cells originating from the thymus." (PMID 28588579, 2017).